STAT3 (signal transducer and activator of transcription 3)
Diseases named in the same sentence as STAT3 in open-access papers (continued):
Sharing a sentence is not in itself a finding about the gene and the disease.
tumor (continued). "Reports suggest that niclosamide inhibits tumor growth promoting pathways, including WNT/beta-catenin, STAT3, Notch, and mTOR pathways, however, its exact antitumor mechanism is not entirely clear." (PMID 30258081, 2018). "STAT3 interacted with CD36, which then interacted with NF-κB; thus, nobiletin inhibited tumor angiogenesis via the CD36/STAT3/NF-κB signaling axis." (PMID 29914089, 2018). "Functional analyses revealed that PLOD3 interacts with STAT3, thereby expressing matrix metalloproteinases (MMP-2 and MMP-9) and with urokinase plasminogen activator (uPA) to enhance tumor metastasis." (PMID 30442941, 2018). "In 3LL-D122-metastasis, of mice treated with the best combination, both EGFR and uPAR/α5β1 integrin pathways are turn off (I.e expression of uPAR/α5β1; and phosphorylation of EGFR, Stat3, Src and FAK are reduced); and tumor angiogenesis is decreased." (PMID 29844873, 2018). "When the glioma stem cell line GSC11 was subjected to hypoxic conditions, HIF-1-induced phosphorylated STAT3 activated ICAM-1 transcription and promoted macrophage infiltration into the tumor tissues." (PMID 29670046, 2018). "In vitro B16F10 cell experiments presented that STAT3 siRNA PEI complex can enhance cellular uptake and transfection of siRNA, correspondingly enhance gene silencing efficiency and inhibit tumor cells growth." (PMID 29348670, 2018). "One of the important roles of STAT3 in ALCL is mimicking physiological progrowth signals, such as IL2 and TCR signaling pathways, allowing for the proliferation and survival of tumor cells." (PMID 29617304, 2018). "These miRNAs are transcriptionally regulated by STAT3, a major substrate for ALK, and promote survival and growth of this tumor." (PMID 30201877, 2018). "The transcription factor STAT3 has been found to be constitutively activated in different tumors including GBM and enhanced tumor radioresistance." (PMID 29423098, 2018). "In a recent study, mice with HCC were treated with a combination of tumor cell lysate- (TCL-) loaded DCs and nifuroxazide, which is an inhibitor of signal transducer and activator of transcription 3 (STAT3)." (PMID 29785403, 2018). "In summary, we found that EEAC at 100 mg/kg significantly inhibits tumor growth in SMMC-7721 cell-bearing mice, as well as induces apoptosis and suppresses STAT3 activation in tumors." (PMID 30618745, 2018). "HEGBC promotes GBC cell proliferation and migration, inhibited GBC cell apoptosis, and promoted tumor growth and metastasis of GBC via forming a positive regulatory loop with IL-11/STAT3." (PMID 30086773, 2018). "Other papers proved that systemic IL-17, through activation of the IL-6/Stat3 pathway and release of MMP2/9, TNF-α, and vascular endothelial factor (VEGF), induces tumor cell migration and metastatic growth in lung cancer-bearing mice." (PMID 30200242, 2018). "The activation of STAT3, STAT5B, and CDKN2A promotes a state of equilibrium and has tumor suppressive activities." (PMID 30325954, 2018). "Our results are consistent with previous observations that STAT3 also plays an important role in promoting EMT and thus invasion and migration of tumor cells." (PMID 29571296, 2018). "NDRG2 can reduce the level of receptor gp130 and inactivate its downstream targets STAT3 and ERK1/2, which leads to decreased EMT and tumor metastasis." (PMID 30591630, 2018). "The hypoxia regulator STAT3 was found to be significantly down-regulated in the GBM50 and GBM0.2 tumours." (PMID 30208958, 2018). "Similar findings were observed after inhibition of the IL-6/STAT3 pathways, leading to a significant inhibition of MDSC expansion and tumor growth of the murine TC1 tumor model." (PMID 30349530, 2018). "Our results further indicated that miR-143-3p inactivated the MAPK/ERK and PI3K/AKT/STAT3 pathways in GBC cells by directly targeting ITGA6, resulting in a decrease in PLGF and the development of GBC angiogenesis and tumour growth." (PMID 29416013, 2018).
tumor (continued). "This study reveals that the expression of MMPs is tightly regulated by local tumor cell density through the synergistic signaling mechanism of Interleukin 6 (IL-6) and Interleukin 8 (IL-8) via the JAK2/STAT3 complex." (PMID 30220965, 2018). "In our study, ectopic expression of Slug rescued the effect of shSTAT3 on repressed stem-like properties, including tumor-initiating capabilities, in GBM-R2I2/sh-STAT3 cells." (PMID 30551687, 2018). "We found that STAT3 is critical for GBM tumorigenesis and that the Y705 phosphorylation site is indispensable for GIC tumor growth." (PMID 29774125, 2018). "Similar to the findings for STAT3, we found in this work that inhibition of SIRT2 significantly attenuated tumour angiogenesis under normal culture conditions." (PMID 30584257, 2018). "For example, kinases such as Fyn and Src have been known to activate STAT3 and drive EMT in many tumor systems." (PMID 30081609, 2018). "We demonstrated the anti-tumor mechanisms of CK on affecting ERS and apoptosis in this process as modulated by STAT3." (PMID 29921768, 2018). "A number of studies have revealed that iron chelation can affect the AKT, ERK, p38, TGF-β, STAT3, JNK, Wnt signaling, and autophagic pathways to consequently suppress tumor growth and metastasis." (PMID 30591630, 2018). "The Janus kinase 2/signal transducer and activator of transcription 3 (JAK2/STAT3) signaling pathway is activated in numerous types of tumors and regulates cell proliferation, angiogenesis, and migration of tumor cells." (PMID 30285793, 2018). "Together, our findings support a notion that G3BP1 promotes tumor progression and metastasis through IL-6/G3BP1/STAT3 signaling axis in RCC." (PMID 29717134, 2018). "Immunohistochemical analysis also demonstrated decreased NF-κB, STAT3, and HIF-1α expression levels in the tumor tissue treated with miR-302b." (PMID 28467773, 2017). "The authors identified CD45- CD90+ CTCs in 91% of samples and demonstrated that this cell population expressed key stem-like genes including Bmi1, CD44, Oct4, Notch1, Wnt3a, Stat3, and HIF-1a compared to CD90+ tumor-tissue cells." (PMID 27738343, 2017). "In conclusion, ponatinib exhibits anti-tumor efficacy in NB by inhibiting FGFR1 signaling and blocking the activation of PI3K/AKT/mTOR and JAK/STAT3 signaling pathways, as evidenced by both in vitro and in vivo assays." (PMID 27564113, 2017). "Forced expression of activated STAT3 in fibroblast cell lines resulted in 3-6 fold up-regulation of MYC, CCND1 (coding for cyclin D1) and BCL2L1 (BCL-XL) mRNA, and permitted tumor formation in nude mice." (PMID 29207662, 2017). "Here, we have demonstrated that the use of specific inhibitors to the pathways which we identified as induced in PIK3CA‐mutant tumors, such as STAT3, β‐catenin, and IGF‐1R, potentiates the cytotoxic effect of PI3K inhibitor on mutant PIK3CA tumor cells." (PMID 28296140, 2017). "The IL-17-induced IL-6 activates STAT3 and increases the expression of pro-angiogenic factors such as IL-8, MMP2, and VEGF to promote angiogenesis and tumor growth in vivo." (PMID 28978186, 2017). "The acetylation and phosphorylation of Stat3 were significantly enhanced in tumors from Hdac7+/−/K-Ras mice and HDAC7-depleted human tumor cell lines." (PMID 29126425, 2017). "Together, these findings demonstrate that STAT3 and STAT6 cooperate in macrophages and enhance tumour progression in a cathepsin-dependent manner." (PMID 29065107, 2017). "In this study, we demonstrate that SH003-induced autophagy via inhibiting STAT3 and mTOR results in an induction of lysosomal p62/SQSTM1 accumulation-mediated reactive oxygen species (ROS) generation and attenuates tumor growth." (PMID 29179443, 2017). "R193A/K195A mutations also impaired EGFR-stimulated cell proliferation, cell migration, colony formation, tumor growth, GSC self-renewal, p-STAT3 and ID1 expression." (PMID 29129908, 2017).
tumor (continued). "Remarkably, this CTC-subset displayed tumor stem-like features, as evidenced by the expression of key stem-like genes including Bmi1, CD44, Oct4, Notch1, Wnt3a, Stat3, and HIF-1α." (PMID 27738343, 2017). "Last, immunohistochemical analysis demonstrated decreased NF-κB, STAT3, and HIF-1α expression levels in the tumor tissue treated with miR-302b." (PMID 28467773, 2017). "When examining consistently altered pathways or kinases across more than one platform, the GNRH, PTEN, STAT3, IL-8, B cell receptor, NF-kB and NO-ROS in macrophages pathways as well as the kinases ERBB2, ERBB3 and SYK were upregulated in tumor tissue." (PMID 28423512, 2017). "The Western blot analyses of 2HF treated tumor tissue lysates, as compared with untreated controls, revealed a decrease in the level of proliferation proteins pAKT, survivin, RLIP76, pERK, pJAK2, STAT3, CDK4 and cyclin B1." (PMID 29088842, 2017). "IL6 was reported to stimulate STAT3 activity which promotes tumor growth and survival of NSCLC via JAK/STAT3 signalling." (PMID 28427199, 2017). "We also found that STAT3 has a role in tumor angiogenesis through PXN and we discovered a new binding site for STAT3 in the PXN gene promoter, which plays an important role in inhibition of tumor angiogenesis by nobiletin." (PMID 28468300, 2017). "According to a recent report, STAT3 and STAT6 were shown to synergistically promote cathepsin secretion by macrophages, thereby enhancing tumour invasion and metastasis." (PMID 29065107, 2017). "The results of our tumor section evaluations by IHC showed that simvastatin treatment increased p21 and p27 expression and AMPK activation and decreased Skp2 expression and STAT3 phosphorylation." (PMID 28230855, 2017). "In many types of tumors, activation of STAT3 increases the expression of VEGF and MMPs, promoting tumor angiogenesis." (PMID 28978186, 2017). "Consistently, we found that simvastatin also increased p21 and p27 expression in tumor sections by reducing Skp2 expression and inducing AMPK activation and STAT3 suppression in the same tumor tissues." (PMID 28230855, 2017). "New evidences also demonstrated that STAT3 promoted cancer progression through participation in EMT, tumor microenvironment regulation and cancer stem cell self-renewal and differentiation." (PMID 27861147, 2017). "An oncogenic fusion protein, paxillin-3-forkhead (PAX3-FKHR) interacts with STAT3 to alter the transcription of various immune-stimulating cytokines and chemokines, and MHC class II molecules in tumor cells." (PMID 28346397, 2017). "In mice with appropriate tumor engraftment, we probed the TME for leukocyte infiltrations between the STAT3 suppressed group and the control group." (PMID 28008146, 2017). "In the present study, we found that IL-6 neutralizating antibody partly suppressed the STAT3 or JAK2 phosphorylation, which suggested that IL-6 contributed partially to the tumor-promoting effect of CAFs on GC cells." (PMID 28186964, 2017). "Tumor cells were pretreated with cisplatin for different time periods, washed and subsequently pulsed with cytokines after which STAT1, STAT3 or STAT6 phosphorylation was assessed." (PMID 28903353, 2017). "On the other hand, L-4F inhibited both the cytokines (IL-4 and IL-17A) producing cells in tumor tissues and the important signaling molecules (phosphorylation of ERK and STAT3)." (PMID 29245934, 2017). "Analysis of excised tumour tissues following treatment revealed that combined treatment dramatically reduced the phosphorylation of ERK1/2, Akt, and STAT3, compared to that with cetuximab alone treatment." (PMID 28489072, 2017). "In another study, inhibition of STAT3 activation in four MPNST lines resulted in decreased wound healing, cell migration, invasion, and tumor formation." (PMID 28825044, 2017).
tumor (continued). "In the present study, we found that high expression of STAT3 correlated with tumor progression and poor prognosis in ICC, suggesting that STAT3 expression promotes proliferation and metastasis in ICC." (PMID 28032598, 2017). "Since STAT3- and JNK-activation are well characterized critical regulators for tumor promotion, the potentiation of their activation in hybrids suggests an additive mechanism enhancing tumor incidence." (PMID 28881751, 2017). "Taken together, these results indicated that simvastatin repressed tumor growth by increasing p21 and p27 expression through AMPK activation and STAT3/Skp2 axis inhibition in vivo." (PMID 28230855, 2017). "We show that tyrosine kinases engage pY239/240-ShcA to sustain STAT3 immunosuppressive signals and simultaneously employ pY313ShcA to restrain activation of STAT1-driven anti-tumour immunity." (PMID 28276425, 2017). "Immunohistochemistry staining demonstrated lower numbers of positive-stained IL-6, STAT3 and HIF1 cells in tumor tissues developed from siRNA-IL-6 knockdown cells, as compared with that of the CSC-derived xenografts." (PMID 28878571, 2017). "It has been previously reported that DR6 is involved in tumor angiogenesis via NF-kB, p38 MAPK and STAT3 pathways." (PMID 28743875, 2017). "Our results showed that simvastatin inhibited tumor growth and that the expression patterns of p21, p27, Skp2, AMPK and STAT3 were similar to those of the in vitro study." (PMID 28230855, 2017). "STAT3 abnormal activity accelerates IL-6, HIF1α and VEGF, specifically in the tumor microenvironment." (PMID 27861147, 2017). "A previous study has shown that STAT3 ablation in tumor cells modulates NKG2D-mediated NK cell activation, and that STAT3 directly interacts with MIC1 promoter to repress MIC1 transcription." (PMID 29221114, 2017). "Taken together, these results demonstrated that CAFs promoted tumor growth in vivo by inducing EMT and activating JAK2/STAT3 pathway." (PMID 29100297, 2017). "Studies have already shown that STAT3 activity upregulates the expression of VEGF and thus tumor angiogenesis." (PMID 28468300, 2017). "For instance, IL-6 can contribute to tumor cell survival and upregulate the antiapoptotic genes by driving JAK2/STAT3 signal; IFN-ɤ activates macrophage by JAK-STAT signaling pathway." (PMID 28630636, 2017). "Consistently, p-STAT3 expression level was high in poorly differentiated region of HNSCC, whereas STAT1 level was high in well-differentiated tumor region." (PMID 28270740, 2017). "For example, miR-27a was found downregulated and showed tumor-suppressive functions in CRC, targeting Stat3 and Smad2, and in other cancers it was also found upregulated and showed oncogenic functions in CRC." (PMID 28441730, 2017). "Tumor cells that survived up to 6–9 days of erlotinib treatment signaled independently of EGFR and MET with early STAT3 reactivation." (PMID 28521301, 2017). "Aberrantly activated RTKs have been reported to promote NB tumor progression through activating signaling pathways such as PI3K/AKT/mTOR and JAK/STAT3." (PMID 27564113, 2017). "We discovered a novel binding site for STAT3 in the PXN gene promoter, which is responsible for tumor angiogenesis inhibition by nobiletin." (PMID 28468300, 2017). "A real-time RT-PCR assay was performed to analyze STAT3 transcripts in frozen paired samples derived from Cohort A patients with ICC and adjacent liver tissues, with 82% (50 of 61) of tumor tissues having higher expression than the adjacent liver tissues." (PMID 28032598, 2017). "Our results suggest that TC-PTP helps protect keratinocytes against tumor initiation and progression by facilitating DMBA-induced apoptosis and inhibiting TPA-induced cell proliferation via the negative regulation of STAT3 and AKT signaling." (PMID 28322331, 2017).
tumor (continued). "The mRNA expression of oncogenic proteins STAT3, IGF1, cyclin D2, and c-MYC increased with respect to increasing glucose concentrations while FOXO1 (tumor suppressor) showed decreased mRNA expression." (PMID 28114390, 2017). "Taken together, these data suggest that tyrosine kinases engage the Y239/240-ShcA phosphorylation sites primarily to potentiate STAT3 immunosuppressive signals and use the Y313-ShcA phosphorylation sites to attenuate STAT1-dependent anti-tumour immunity." (PMID 28276425, 2017). "Silencing STAT3 in HER2+ BC cells reduces tumor invasion suggesting a cooperation between HER2 and STAT3 in tumorigenesis." (PMID 28445439, 2017). "The STAT3-blocked whole-cell hepatoma vaccine can augment the cellular and humoral immune responses against HCC, resulting the inhibition of tumor growth and tumorigenesis." (PMID 29115974, 2017). "Immunoreactive IL-6, STAT3 and HIF1 cell numbers were markedly reduced in IL-6 knockdown tumor tissues." (PMID 28878571, 2017). "In this model, TNF-α as a tumor promoter stimulates TNFR1, followed by NF-κB and/or p38/MAPK signaling leads to the activation of transcriptional factor STAT3, which results in the up-regulation of oncoprotein HBXIP." (PMID 28938560, 2017). "Our previous findings confirmed that blocking the STAT3 signaling pathway in HCC cells inhibited proliferation and promoted the apoptosis of tumor cells." (PMID 29115974, 2017). "First, we analyzed the protein expression in tumor tissue by Western blot and find that phosphorylated JAK and STAT3 were both reduced after treatment (P < 0.01 for JAK, P < 0.001 for STAT3)." (PMID 28764703, 2017). "IL-17 and IL-22 enhances IL-23 protumourigenic activity which enhance tumour growth and survival through JAK/STAT3 by activation of IL-6 results in cellular proliferation, angiogenesis, and tumour progression." (PMID 28275390, 2017). "Therefore, SHP2 is a tumor suppressor that may counteract STAT3 activity in the liver." (PMID 28460481, 2017). "In this study, we first reported that BMX can promote cell proliferation and tumor progression through the PI3K/AKT/mTOR and STAT3 pathways." (PMID 28514765, 2017). "To demonstrate a correlation between STAT3 and the levels of CCT2 in tumors from SCLC patients, we used TMAs containing SCLC tumor cores for analysis of both CCT2 and STAT3." (PMID 29299146, 2017). "Taken together, these results indicate that bosutinib effectively inhibits NB tumor growth in vivo by blocking the activities of Src and c-Abl and by blocking the PI3K/AKT/mTOR, MAPK/ERK, and JAK/STAT3 signaling pathways." (PMID 27903968, 2017). "Interleukin-6 (IL-6) is a cytokine present in tumor microenvironment and can promote EMT through enhancing STAT3, MAPK and Akt signaling." (PMID 29088764, 2017). "STAT3 is hyperactivated in IBC, as demonstrated by a high incidence of phosphorylated STAT3 in tumor tissues and also elevated upstream cytokines such as IL6 known to activate this pathway." (PMID 28107181, 2017). "After dual confocal immunofluorescence reactions, tumor vessels appeared lined by endothelial cells expressing both FVIII and Stat3 signals while in the control brain tissue only FVIII+ vessels were detectable." (PMID 28415725, 2017). "As expected, metformin significantly decreased the relative mRNA levels of JAK, STAT3 and c-MYC in tumor tissues." (PMID 29088816, 2017). "Immunohistochemistry of tumor tissues showed that SKLB-850 efficiently inhibited the activation of Syk/ERK, Src/FAK and JAK2/Stat3 pathways." (PMID 29340070, 2017). "This activation leads to phosphorylation of STAT1, STAT3, STAT5, ERK1/2, AKT and mTOR and goes on to drive EMT and promote invasion, migration, and proliferation for tumor progression." (PMID 28223541, 2017).